IL1B (interleukin 1 beta)
Diseases named in the same sentence as IL1B in open-access papers (continued):
Sharing a sentence is not in itself a finding about the gene and the disease.
tumor (continued). "We also showed that TNF-α and IL-1β upregulate the expression of OPN in tumor cells and macrophages; thus, these factors may be candidate targets through which antitumor efficacy can be enhanced." (PMID 39726047, 2024). "Moreover, IL-1β antibody treatment inhibited tumor progression and boosted antitumor immunity in mice by reducing inflammation and promoting M1 macrophage maturation." (PMID 38957317, 2024). "The granulocyte–macrophage colony-stimulating factor is one of the downstream effects released via IL-1β, which enhances the synthesis of M2-type macrophages and myeloid-derived suppressor cells (MDSCs) for promoting tumor invasion, immune escape, and tumor growth." (PMID 38103126, 2024). "Functionally, M1 type macrophages activate the immune response mainly through the production of pro-inflammatory cytokines (e.g., tumour necrosis factor-α [TNFα], interleukin-1β [IL-1β], interleukin-6 [IL-6]) and inhibit tumour growth and spread by phagocytosis and killing of tumour cells." (PMID 39070147, 2024). "The resulting release of IL-1β further promotes tumor growth and metastasis." (PMID 38649701, 2024). "Moreover, activated human THP-1 macrophages released IL-1β after sorafenib administration, while 3D Hep3B spheres displayed increased tumor growth after IL-1β addition, pointing to the liver microenvironment as a key player in inflammasome action." (PMID 38672578, 2024). "Furthermore, ailanthone induced the expression of the inflammatory factors TNF-α, IL-1β, and IL-6 in tumour tissues." (PMID 39723259, 2024). "The current finding that ST6GAL1 expression is induced by IL-1β and IL-6 suggests that the inflammatory milieu associated with PDAC may act in concert with tumor-intrinsic mechanisms to promote high levels of ST6GAL1 expression." (PMID 39260693, 2024). "This pro-tumor function may be attributed to the release of inflammatory cytokines, such as IL-1β, following GSDMD pore formation." (PMID 38898209, 2024). "No inflammation or angiogenesis occurred in IL-1β-deficient mice, and IL-1β-deficient mice showed no local tumor growth or lung metastasis compared to wild-type mice." (PMID 38957317, 2024). "Next, we aimed to determine whether the observed increase in IL-1β gene expression translated into protein expression and secretion by the tumor cells." (PMID 39801513, 2024). "By creating an inflammatory microenvironment within the tumor, IL‐6 and IL‐1β may promote tumor‐cell proliferation by activation of transcription factors and angiogenesis by the induction of key factors such as vascular endothelial growth factor (VEGF)." (PMID 38217262, 2024). "Our data suggests that IL-1B may play a more dominant role in regulating T-cell recruitment into the tumor microenvironment." (PMID 38346068, 2024). "We hypothesize that the IL-1β/1RA axis may express a positive correlation with Ki-67 in terms of tumor potential among patients with invasive BC." (PMID 38397123, 2024). "Additionally, research has highlighted the role of nitric oxide (NO) in fostering chemoresistance in pancreatic cancer by stimulating IL-1β secretion in tumor cells, thereby safeguarding them against anticancer drugs." (PMID 39493763, 2024). "In order to investigate whether EEBR inhibits NSCLC progression in vivo via the NF‐κB‐NLRP3‐GSDMD pathway by promoting pyroptosis, we evaluated the levels of IL‐1β and IL‐18 in tumour tissues." (PMID 38214430, 2024). "Inflammasome activation in liver cells, including hepatocytes, hepatic stellate cells, and immune cells, can lead to the release of pro-inflammatory cytokines, such as IL-1β and IL-18, which can promote inflammation and contribute to cancer promotion in the tumor microenvironment." (PMID 38672578, 2024). "Exosome transporter high-mobility group box 1 (HMGB1) derived from gastric cancer cells induces neutrophil autophagy via the HMGB1/Toll-like receptor 4 (TLR4)/nuclear factor-κB (NF-κB) signaling pathway, releasing pro-tumor cell migration factors, such as IL-1β and OSM." (PMID 38760815, 2024).
tumor (continued). "Moreover, tumour derived IL-1B also triggered the paracrine feed-forward signalling to stimulate malignant invasive ability of cancer-associated fibroblasts (CAFs)." (PMID 38800348, 2024). "Reduced the levels of IL-1β, IL-6 and tumour TNF-α in cerebral tissue." (PMID 38585461, 2024). "A correlation analysis was performed on the levels of 12 CKs in the patients’ serum and the degree of tumor differentiation, revealing a significant correlation between IL-1β (P ═ 0.008), IL-6 (P ═ 0.005), and IL-8 (P ═ 0.05) levels and the degree of tumor differentiation." (PMID 38920620, 2024). "In order to test if sorafenib could act through the activation of the inflammasome in tumor-associated macrophages (TAMs), PMA-activated THP-1 cells were treated with sorafenib and MCC950, and IL-1β production was detected in the cellular media after 16 h." (PMID 38672578, 2024). "Additionally, IL1B and PTGS2 (COX‐2), key players in inflammation, are also linked to tumour growth, angiogenesis and metastasis across various cancer types." (PMID 39629503, 2024). "IL‐1β and IL‐18 are initiating anti‐tumour immune indispensable core players." (PMID 38652105, 2024). "Additionally, we observed upregulation of IL-1β target genes IL-8, VEGF, CCL5, and MMP2 in SUM159, MCF12A and MDA-MB-231 cells This upregulation indicates functional activation of IL-1β signaling in tumor cells co-cultured with B cells." (PMID 39801513, 2024). "Moreover, PDTC decreased the TNF-α- and IL-1β-induced increase in the proliferation and migration abilities of tumor cells." (PMID 39726047, 2024). "Notably, this subset also expressed many genes associated with inflammatory CAFs (iCAF), a population of mesenchymal cells found in neoplastic tissues and predicted to respond to stimuli such as TNFα and IL-1β in the tumor microenvironment." (PMID 39485038, 2024). "Additionally, EVs from CRC stem cells promote tumor initiation by upregulating IL-1β expression to enhance neutrophil survival." (PMID 38802814, 2024). "Furthermore, we analyzed the correlation between LINC00665 levels in metastatic lung cancer patients and immune-suppressive cytokines (TGF-β, IL-10, and IL-1β) as well as anti-tumor cytokines (IFN-γ, IL-2, and TNF-α)." (PMID 38951802, 2024). "Pyroptosis has dual effects on cancer because it is accompanied by the release of inflammatory factors IL-1β and IL-18, and inflammatory factors may have some adverse effects on the tumor microenvironment (TME) during BC development." (PMID 39273650, 2024). "We can speculate that the sample principle follows an IL-1β expression in BC, where the decrease in interleukin levels might promote early phases of tumor development." (PMID 38397123, 2024). "We examined the expression of IL-1β cytokine in control and tumor-bearing groups." (PMID 39394174, 2024). "IL-1B has been shown to promote tumor survival, proliferation, and metastatic potential." (PMID 38346068, 2024). "Moreover, in HCC, TAMs express high levels of SLC40A1, a marker gene encoding ferroportin, which activates Toll-like receptor (TLR) stimulation to produce IL-1β, IL-6, and IL-23, thus shifting innate immunity processes toward tumor-favoring activity." (PMID 39766202, 2024). "Besides IL-12, the expression of cytokines such as TNF-α, IL1β and IL-6 is also critical for the activation of anti-tumour immune responses." (PMID 39487861, 2024). "In addition, it significantly inhibits the expression of NF-κB signaling dependent proinflammatory genes IL-6 and IL-1B through RAD51, thus blocking the STING-associated anti-tumor immunity in stromal tumor-infiltrating lymphocytes (sTILs)." (PMID 39638799, 2024). "The results of animal experiments showed that overexpression of IL-1β led to the promotion of tumor growth and metastasis in vivo, suggesting that IL-1β could be a potential therapeutic target for ESCC treatment." (PMID 38762529, 2024). "Inhibiting SPP1 + Mac-derived TNF-α and IL-1β suppressed tumor growth both in vivo and in vitro." (PMID 39726047, 2024).
tumor (continued). "In addition to recruiting TAMs and other protumoral inflammatory cells to the tumor, roles for IL-1β in growth, invasion, angiogenesis, metastases, stemness, and epithelial-to-mesenchymal transition have been extensively described." (PMID 39475614, 2024). "In addition to studying the effects of TNF-α and IL-1β on tumor cells, we explored their effects on adjacent macrophages." (PMID 39726047, 2024). "It was suggested that inosine might have inhibited tumor invasion and malignant progression by suppressing the overexpression of TNF-α and IL-1β secreted by M1 macrophages, which in turn inhibited tumor invasion and malignant progression." (PMID 39795180, 2024). "Cancer cells can produce IL-1β, which is involved in tumor promotion and angiogenesis." (PMID 39519758, 2024). "The release of pro-inflammatory cytokines such as IL-1β and IL-18 can promote tumor growth and angiogenesis, while sustained inflammation may lead to immune suppression, hindering effective anti-tumor responses." (PMID 39769450, 2024). "IL-1β-positive macrophages were, however, found in tumours from older patients as well." (PMID 38480935, 2024). "We propose that high densities of TIBs may promote aggressive tumor characteristics by activating the IL-1β-NFκB pathway early in the disease, a role that may be distinct from their involvement in anti-tumor immune responses." (PMID 39801513, 2024). "Recently, a study revealed that NAFLD could promote CRC liver metastasis (CRLM) by promoting IL-1β and VEGF production from tumor-associated macrophages (TAMs) educated by the lipid-rich hepatic microenvironment." (PMID 38263401, 2024). "IL-6, IL-1β, and IL-8 all of which are known to be implicated in tumor progression were either downregulated or non-significantly upregulated." (PMID 39427065, 2024). "Notably, IL-1β, a pro-inflammatory cytokine, was among the top upregulated genes in tumor cells co-cultured with both B cell types." (PMID 39801513, 2024). "Furthermore, by analyzing patient tumor samples, the researchers discovered that the increased expression of IL-1β in primary tumors was strongly correlated with adverse clinical outcomes and a significantly increased likelihood of developing bone metastasis." (PMID 38334625, 2024). "In addition, SPP1 + Mac-derived TNF-α and IL-1β promoted the expression of OPN in both tumor cells and macrophages." (PMID 39726047, 2024). "Moreover, IL-1β signaling has been shown to interact with IL1B+ TAMs in tumor cells, creating a positive feedback loop that continuously promotes PDAC progression." (PMID 38982491, 2024). "We found that TNF-α and IL-1β could increase the expression of OPN in both tumor cells and macrophages, which might be the reason for the increased number of SPP1 + Macs." (PMID 39726047, 2024). "IL-1B from osteoblasts has been shown to facilitate adhesion of circulating tumour cells to sinusoidal endothelial cells by increasing the expression of vascular cell adhesion molecules such as intercellular adhesion molecule 1 (ICAM-1), vascular cell adhesion molecule 1 (VCAM-1), and E-selectin." (PMID 38800348, 2024). "In tumor tissues, IL-1α, IL-1β, IL1R1, IL1RL1, IL1F10, IL33, CASP1, and AIM2 are highly expressed." (PMID 39461030, 2024). "In summary, our findings indicate that B cells may promote the aggressive nature of TNBC early in the disease by upregulating activity of IL-1β-NFκB signaling in tumor cells leading to increased motility and invasiveness." (PMID 39801513, 2024). "Similarly, NLRP3 inflammasomes promote melanoma growth by activating caspase-1 and producing IL-1β, which leads to suppression of anti-tumor immunity generated by NK cells and T cells." (PMID 37020871, 2023). "GC cells p65/INHBB/activin B and fibroblasts p65/IL-1β signal loop led to the formation of a whole tumor-promoting inflammatory microenvironment, which might be a promising therapeutic target for GC." (PMID 37858201, 2023).
tumor (continued). "Considering that inflammasomes may initiate pyroptosis in tumor cells and that IL-1β and IL-18 have been shown to activate T cells and NK cells, inflammasome activators may improve the effects of immune checkpoint inhibitors." (PMID 36932407, 2023). "Furthermore, the surgical treatment released mt‐DAMPs, that contributed to the pre‐metastatic niche formation and stimulated the upregulation of IL‐1β signal, which is critical in the settlement of circulating tumor cells in lungs after surgery." (PMID 37585564, 2023). "Interestingly, primary tumor volume was similar between WT and Il1b−/− mice, but pulmonary metastasis was significantly decreased in Il1b−/− mice compared with WT mice as shown by H&E staining and qPCR analysis of luc2." (PMID 37443052, 2023). "We also observed higher IL-1β level in the hippocampus in HCC tumor-bearing mice, suggesting tumor-induced microbiota alteration might affect the hippocampal STC through IL-1β signaling." (PMID 37400621, 2023). "Small amounts of IL-1β induce a specific immune response with limited inflammation, but the overexpression of IL-1β gives an extensive inflammation and tissue damage and enables tumor invasiveness." (PMID 38187473, 2023). "In addition, A549 tumor CM significantly enhanced the cleavage and maturation of inflammasome components caspase-1 and IL-1β and upregulated AIM2." (PMID 37449203, 2023). "The IL-1β gene is highly expressed in the tumor microenvironment, particularly in macrophages." (PMID 37441079, 2023). "Moreover, depletion of the type I IFNs and IL‐1β cytokines abrogate tumor regression in mice bearing the Arf1‐ablated tumor cells." (PMID 37786300, 2023). "These cells have been thought to control tumor progression through various effects, including regulation of angiogenesis and differentiation of cancer stem cells as well as modification of immunity, similar to the reported functions of IL-1β." (PMID 37441079, 2023). "Besides IL-1β, IL-18 secreted by tumor cells through NLRP3 is positively correlated with PD-L1 expression and negatively correlated with cytotoxic T cells." (PMID 36932407, 2023). "Next, we examined whether IL-1β treatment of CAFs affects tumor cell behavior by assessing growth and invasion of tumor cells in 3D spheroid assays (assay A)." (PMID 37460545, 2023). "Notably, in breast cancer, Th-17 cells are positively related to IL-6, IL-1β, and IL-17 expression and negatively correlated with increased metastatic lymph nodes and tumor cell angiogenesis." (PMID 36993955, 2023). "Indeed, MUC1-targeting CAR Ms showed potent anti-tumor function by phagocytosis and secretion of pro-inflammatory cytokines such as IL-1β, IL-8, and TNFα in the presence of MUC1 expressing tumor cells from solid lung tumors or malignant pleural effusions." (PMID 38017494, 2023). "As a vital inflammatory cytokine, IL1B might drive a new tumor subtype that could be reflected in overall survival (OS) and predicted using the radiomics method." (PMID 36969073, 2023). "Unfortunately, the use of IL‐1α or IL‐1β as anti‐cancer agents in clinical trials have not lived up to the initial excitement caused by the observed preclinical anti‐tumor immune responses." (PMID 37206237, 2023). "Collectively, we show that tumor‐released lactate could trigger IL‐1β secretion from Mφ by activating the NLRP3 inflammasome." (PMID 37009412, 2023). "Thus, it is possible that the aberrant expression of IL-1Ra in cancer cells inhibits the anti-tumor role of IL-1β in APC-mediated T cell activation, thereby contributing to a subtype of gemcitabine, or other types of chemotherapies, resistant PDA." (PMID 37563620, 2023). "Some groups reported that mice with deficient inflammasome components were more susceptible to CRC than the control group, and showed accelerated tumor growth proportionally to attenuated levels of IL-1β and IL-18, the latter mediating NK cell tumoricidal activity." (PMID 37891577, 2023).
tumor (continued). "Within the TME, tumor cells are the source of chronic inflammation, and IL-1β becomes an upstream regulator, altering immunologic responses, hormonal signaling, neovascularization, and enhancing metastatic potential through downstream pathways such as NF-κB/MAPK/Protein Kinase B (AKT)/Wnt/β-catenin." (PMID 37511306, 2023). "CTX administered concomitantly with the inoculation of tumor cells and the peritoneal lavage performed on the 6th day of this procedure no change was observed in the production of NO• or in the secretion of the IL-1β." (PMID 37888647, 2023). "Prior studies have indicated that TNFα, IL-1β, IL-6 promote tumor growth in obese mouse models." (PMID 37954072, 2023). "Local antagonism of IL-1β or IL-1R1 prolongs the survival of tumor-bearing mice." (PMID 37733448, 2023). "On the one hand, pyroptosis is accompanied by IL-1β and IL-18 release, which could mediate tumor-promoting inflammation." (PMID 36941988, 2023). "IL-1β tumor mRNA levels were undetectable when using human primers across all cohorts." (PMID 37092555, 2023). "IL1β has an established role in angiogenesis across multiple tumor types." (PMID 37065483, 2023). "Blocking IL-1β rescued the STC in the HCC tumor-bearing mice." (PMID 37400621, 2023). "Based on the data presented above, we hypothesized that chronic HDM exposure changes the lung TME and makes it conducive to tumor growth by triggering IL-1β-mediated inflammation." (PMID 36670473, 2023). "Moreover, M-MDSC produces IL-1β, which in turn upregulates E-selectin expression, favouring tumour cell arrest on endothelial cells, in preclinical cancer models." (PMID 36161514, 2023). "Using a natural mutation in the Ncf1 gene (encoding a cytosolic component of the NADPH oxidase 2 [NOX2] complex), a group identified that Ncf1 competent neutrophils exhibited functional induction of ROS and IL‐1β signaling, thus promoting lung colonization by tumor cells." (PMID 38062888, 2023). "Il1b genetic ablation prolongs the survival of tumor-bearing mice." (PMID 37733448, 2023). "The observed reduction in tumor burden and tumor size in TG mice was associated with decreased expression of inflammatory cytokines such as Il-1b, Il-6, Il-17, and Ccl2 in the tumor and tumor-adjacent tissue, as well as a likely reduction in tumor-infiltrating immune cells." (PMID 38090485, 2023). "Importantly, IL‐1β neutralizing antibody significantly curbed tumor growth and displayed synergistic antitumor efficacies with anti‐PD‐L1 antibody in tumor‐bearing mouse models." (PMID 37009412, 2023). "IL-1β may promote drug resistance and tumour survival and is emerging as a prognostic factor for patients in response to targeted therapy, making IL-1β a possible target that may need to be taken into consideration." (PMID 37550397, 2023). "The tumor cells showed morphological and molecular features indicating that they kept the expression of malignancy markers acquired by their treatment with IL-1β and its activation of the IL-1β/IL-1RI/β-catenin pathway." (PMID 37686042, 2023). "Furthermore, there is a marked reduction in the expression of IL-1α and IL-1β in the tumor tissues of Anakinra treated mice compared to control groups." (PMID 38152619, 2023). "Similarly, TAMs induce pro-inflammatory cytokines (IL-23, IL-6, and IL-1β), facilitating tumor development and progression." (PMID 37892995, 2023). "Thus, the data suggest a feed-forward loop in which PDGFB-driven GBM cells express MCPs that drive BMDM infiltration and IL-1β expression, further promoting tumor growth." (PMID 37966120, 2023). "Additionally, TAN-secreted IL-1β and MPs promote tumor cell exodus towards premetastatic niches for invasion and metastasis." (PMID 38093246, 2023). "When inhibiting the expression of LncRNA-XIST oncogene, it could activate NLRP3 inflammatory bodies, increase the expression of caspase-1 and IL-1β, and then induce pyroptosis of tumor cells, ultimately inhibiting the occurrence and development of NSCLC." (PMID 37194012, 2023).